HDAC2 (histone deacetylase 2)
Diseases named in the same sentence as HDAC2 in open-access papers (continued):
Sharing a sentence is not in itself a finding about the gene and the disease.
glioma (continued). "Therefore, inhibition of HDAC2 may help to reduce the invasiveness of glioma cells and improve the sensitivity to treatment." (PMID 38985240, 2025). "The mRNA expression of HDAC1, HDAC2, HDAC3, HDAC6 and PI3K/AKT1 was analyzed in GBM and low grade glioma tissues." (PMID 40297576, 2025). "In glioma cells, strong nuclear expression of HDAC1, HDAC2, and NCOR2 has been observed, while NCOR1 and HDAC3 show weaker expression." (PMID 40940748, 2025). "In this study, we found that the HDAC2 was positive-correlated with the expression of CNOT7, HDAC2 upregulated CNOT7 expression in glioma cells." (PMID 38985240, 2025). "In gliomas, targeting HDAC1 and HDAC2 has been shown to potentially inhibit tumor progression and enhance glioblastoma cell sensitivity to treatment." (PMID 41331688, 2025). "Ten glioma samples (5 IDH1 wildtype and 5 IDH1 mutant) were stained for various HDAC genes using internally validated antibodies (HDAC1, HDAC2, HDAC3, HDAC4, HDAC5, HDAC6 and HDAC7) and scored by a blinded neuropathologist (AK)." (PMID 37528157, 2023). "The glioma cells show on average 90% higher HDAC1, 108% higher HDAC2 and 23% higher HDAC3 protein expression than astrocytes." (PMID 35365623, 2022). "Notable genes with SNV-associated increased expression include TERT, COPS3, POLE2 and HDAC2—involving multiple cancer types—MYC, BCL2, PIM1 and IGLL5—involving lymphomas—and CYHR1—involving pediatric low-grade gliomas." (PMID 33554123, 2021). "Considering the findings from ONCOMINE, GEPIA, and CGGA, HDAC1, HDAC2, and HDAC11 were thus verified for their differential expression in glioma." (PMID 34540896, 2021). "Additionally, the strong nuclear expression of HDAC1, HDAC2, and NCOR2 in glioma cells, along with weak expression of NCOR1 and HDAC3, suggests a potential role for these proteins in tumor progression and as markers for patient prognosis." (PMID 40940748, 2025). "Although high HDAC1 and HDAC2 expression is related to glioma aggressiveness and proliferation, to date, no drugs have been approved for glioblastoma treatment." (PMID 41331688, 2025). "The OS analysis based on GEPIA revealed that the glioma patients with high expression levels of HDAC1 (HR:3.9, p < 0.0001), HDAC2 (HR:1.3, p = 0.024), HDAC3 (HR:4.4, p < 0.0001), and HDAC7 (HR:3.3, p < 0.0001) would face with more risks compared to the ones with low expression of these genes." (PMID 34540896, 2021). "In contrast to less efficient discrimination of HDAC2 and HDAC11, the AUC value of HDAC1 over 0.7 throughout the time points manifested that HDAC1 was identified to be a promising prognostic biomarker for glioma." (PMID 34540896, 2021). "Conversely, HDAC2 expression was not significantly correlated with the grade of glioma and was correlated with better prognosis." (PMID 32938908, 2020). "While it is known that HDAC1 and HDAC2 (class I HDACs) harbor highly specific and nonoverlapping roles in the developing brain, it is unclear whether these nonredundant functions are retained in glioma cells." (PMID 34494550, 2021).
Cognitive impairment (19 papers, 2018 to 2024). Abnormal cognition is characterized by deficits in thinking, reasoning, or remembering. "The post‐hoc analysis revealed that MSD‐induced offspring's cognitive impairment was associated with an increased HDAC2 mRNA and protein and a decreased CBP mRNA and protein, while EE reversed it." (PMID 37073496, 2023). "Elevated HDAC2 modifies transcription in hippocampal neurons and impacts microglial activity during neuroinflammation-induced cognitive impairment." (PMID 38455734, 2024). "These alterations in histone acetylation contribute to cognitive impairment, while selective inhibition of histone deacetylase 2 (HDAC2) is potent in maintaining the homeostasis of histone acetylation and reversing cognitive deficits." (PMID 34194489, 2021). "In the following experiments, we focused on the HDAC2-mediated mechanism of LPS-induced cognitive impairment." (PMID 31796106, 2019). "Previous studies demonstrated that cognitive impairment is highly related to HDAC2, and repeated exposure to ISO in aged rats upregulated HDAC2 expression." (PMID 31796106, 2019). "In concur with other recent works which presented evidences of histone deacetylase-2 as player in stress-induced cognitive impairment via histone deacetylation and PI3K/AKT pathway modulation, our results are consent with these published studies." (PMID 30349449, 2018). "Our findings suggest that HDAC2 is involved in extrinsic stress-induced cognitive impairment." (PMID 38635564, 2024). "Unlike HDAC1, PET neuroimaging and other postmortem studies have confirmed that the expression of HDAC2 is decreased in the dorsolateral prefrontal cortex of SCZ patients, which may be associated with cognitive impairment." (PMID 36406755, 2022). "Therefore, promoting histone acetylation, inhibiting the production of HDAC2, or promoting its degradation can be potential strategies for the treatment of general anesthetic neurotoxicity and cognitive impairment in the developing brain." (PMID 36504660, 2022). "Accordingly, suppressing HDAC2 in the hippocampus may be an approach for inflammation-induced cognitive deficits." (PMID 31796106, 2019). "In aged rats, it is reported that sodium butyrate (histone deacetylase inhibitor) not only reverses the signaling changes including down-regulation of HDAC2 and restoration of BDNF expression but also rescues cognitive impairment caused by repeated isoflurane exposure." (PMID 30341248, 2019). "The upregulation of HDAC2 and HDAC3 has been observed in the hippocampus of offspring exposed to sevoflurane during late pregnancy on PND 1 and PND 35 accompanied with long‐term cognitive impairment." (PMID 37073496, 2023). "Additionally, EE improved traumatic brain injury‐ and sevoflurane‐induced cognitive impairment by increasing CBP expression and decreasing HDAC2 expression, respectively." (PMID 37073496, 2023). "In fact, there are numerous cognition-related histone modifications studies of SCZ and ASD, but there are still few histone studies focusing on cognitive impairment in BD and MDD, and studies of the expression of HDAC2 have been inconsistent between human and mice." (PMID 36406755, 2022). "Thus, our finding of HDAC2 overexpression in the CC and blood leucocytes of MDD patients could reflect both a failure in the implementation of an adaptive mechanism and a marker of cognitive deficits." (PMID 30377985, 2019).
Stroke (18 papers, 2018 to 2026). Sudden impairment of blood flow to a part of the brain due to occlusion or rupture of an artery to the brain. "Conversely, HDAC2 deletion reversed the downregulation of synaptic proteins and parvalbumin induced by stroke, thereby promoting functional recovery in the brain." (PMID 40356977, 2025). "After I/R, oxidative stress activates HDAC2, and blocking HDAC2 can improve cellular survival and neurogenesis after stroke." (PMID 39649720, 2024). "The stroke insult-related genes were Nfkb1, histone deacetylase 2 (Hdac2), and sirtuin 1 (Sirt1) in the vs. MCAO+tDCS-FN(cA) and U2 small nuclear RNA auxiliary factor 2 (U2af2) in the vs. MCAO+tDCS-FN(iC-cA) configurations." (PMID 38389833, 2024). "Inhibiting HDAC2 using non-selective inhibitors such as MGCD0103, SAHA, and TMP269 was found to promote neuronal survival, suppress neuroinflammation, and improve motor function post-stroke, highlighting the critical role of HDAC2 in recovery." (PMID 39519209, 2024). "HDAC2 inhibition at 5 to 7 post-stroke days promoted survival and neuroplasticity of neurons, suppressed neuroinflammation, recovered motor functions, and improved the stroke outcome." (PMID 34680562, 2021). "The comparison of their effects showed the critical role of HDAC2 inhibition in the restoration of brain function, whereas HDAC2 overexpression exacerbated the stroke-induced functional disorders." (PMID 34680562, 2021). "The upregulation of HDAC2 observed in the early recovery phase from five to seven post-stroke days reduced survival of neurons and augment neuroinflammation." (PMID 34680562, 2021). "The penumbra of HDAC2 in the rat cerebral cortex enhanced 4 or 24 hours after photothrombotic stroke (PTS)." (PMID 32963637, 2020). "HDAC2 is activated by oxidative stress post I/R, and inhibition of HDAC2 increases cell viability and neurogenesis post-stroke 27-29." (PMID 32863951, 2020). "Consistently, pan-HDACs inhibitors and the specific inhibitor of class І HDACs, including HDAC2, alleviate stroke-induced neurological deficits facilitating post-stroke recovery in mice." (PMID 30208931, 2018). "Hdac2 expression was markedly increased in the peri-infarct cortex after cerebral stroke, and Hdac2 knockdown contributed to mouse motor function recovery after stroke by increasing the expression of neurotrophins and neuroplasticity-related proteins." (PMID 36062010, 2022). "HDAC2 targeting is apparently a novel therapeutic strategy for stroke recovery." (PMID 34680562, 2021). "Interestingly, ischemic stroke prominently upregulates HDAC2 in astrocytic processes and end-feet, suggesting HDAC2 affects the NVU post-stroke." (PMID 31543756, 2019). "Recently, it has been demonstrated that suppressing HDAC2 in the peri-infarct cortex of rodents promotes the motor function recovery at day 8 after stroke, opening a new therapeutic window for the treatment of stroke." (PMID 29316653, 2018). "HDAC2 may be a key mediator of post-stroke motor dysfunction." (PMID 40356977, 2025). "Recent studies have shown that BHB promotes stroke recovery in rodents by reversing stroke-induced GABA transporter-1 (GAT-1) downregulation and dysfunction through HDAC2/3 inhibition, enhancing neural circuit excitability and functional plasticity." (PMID 38203294, 2023). "Long-term overexpression of HDAC2 and HDAC8 was observed in neurons and astrocytes at 3‒14 days after photothrombotic stroke in the mouse cerebral cortex." (PMID 34680562, 2021). "The administration of α-phenyltroplon that inhibits both HDAC2 and HDAC8, or MI-192, an inhibitor of HDAC2 and HDAC3, suppressed apoptosis of cortical cells in the penumbra and decreased the infarct volume after photothrombotic stroke in mice." (PMID 34680562, 2021). "In particular, HDAC2 and HDAC6 are involved in the stroke-induced death of neurons in the ischemic brain." (PMID 34680562, 2021).
Stroke (continued). "Mature OLs showed a retained increase of HDAC2 following stroke, while HDAC1 levels were decreased, indicating that individual HDACs family members play distinct roles during recovery after stroke." (PMID 31614602, 2019). "Consistent with the notion that HDAC2 is a critical factor in EE-mediated stroke recovery 36, HDAC2 but not HDAC1 knockdown upregulated GAT-1 expression." (PMID 33664860, 2021).
leukemia (17 papers, 2008 to 2024). A malignant (clonal) hematologic disorder, involving hematopoietic stem cells and characterized by the presence of primitive or atypical myeloid or lymphoid cells in the bone marrow and the blood. "HDAC2 is implicated in epigenetics and have been shown to be associated to CFTR expression for PTEN-pathway regulation in Ph+ leukemia cell lines." (PMID 32517078, 2020). "As such, application of HDAC2 with TPA treatment for the leukemia therapy should be considered cautiously." (PMID 30142192, 2018). "Previous studies showed that HDAC inhibitors induce differentiation of leukemia by inhibiting the catalytic activities of HDAC2." (PMID 30142192, 2018). "As GATA1 is a master regulator of erythropoiesis and K562 is a leukaemia derived cell line, the HudsonAlpha HDAC2 experiment (and antibody) appears more reliable than the Broad HDAC2 in K562." (PMID 26619763, 2015). "Therefore, the study of enzyme activity-independent regulation by HDAC2 can be an attractive model for understanding the mechanisms of leukemia cell differentiation." (PMID 30142192, 2018). "The fact that histone deacetylase recruitment resulted in increased histone acetylation may indicate that HDAC2 can regulate gene expression in leukemia in a histone deacetylase activity-independent manner." (PMID 30142192, 2018). "Interestingly, we observed that Hdac1Δ/Δ; Hdac2Δ/Δ Eμ-myc mice had significantly lower PBL counts, compared to control Hdac1+/+; Hdac2+/+ Eμ-myc mice, and hence reduced leukemia burdens." (PMID 27886239, 2016). "In addition, a colony formation assay was performed in sh2 and scr U937 cells, corroborating the finding that HDAC2 silencing reduces proliferation and colony formation in leukemia cells." (PMID 25473896, 2015). "Knockdown of HDAC2 induces apoptosis of leukemia cells, which is different from HDAC1 knockdown." (PMID 25341045, 2014). "Chidamide is an oral selective histone deacetylase (HDAC) inhibitor that selectively inhibits HDAC1, HDAC2, HDAC3, and HDAC10, inducing apoptosis and growth arrest in leukemia cells." (PMID 39040100, 2024). "The same experiment performed using the leukemia cell line MV4-11 validated HDAC1 (Kdapp = 16 μM), HDAC2 (Kdapp = 14 μM), and HDAC6 (Kdapp = 21 μM) and identified HDAC3 (Kdapp = 13 μM) and HDAC10 (Kdapp = 5 μM) as additional targets of (R/S)-LM." (PMID 37322067, 2023). "HDAC2 degradation by high VPA level may lose not only enzyme activities, but also enzyme activity-independent roles, which facilitated leukemia differentiation in this study." (PMID 30142192, 2018). "To investigate the significance of Class I HDACs (HDAC1, HDAC2, HDAC3, and HDAC8), HDAC11, and Klfs (Klf1, KLf3, Klf4, and Klf7) in the pathogenesis of human leukemia, we used real-time RT-PCR to evaluate the expression of HDACs and Klfs in bone marrow samples from human leukemia patients." (PMID 25341045, 2014).
liver cancer (16 papers, 2011 to 2025). An epithelial or non-epithelial malignant neoplasm that arises from the liver. "Our results demonstrated that HDAC2 inactivation caused the suppression of tumor cell growth in various liver cancer cell lines." (PMID 22132221, 2011). "Melittin also prevents the HepG2 liver cancer cell progression through the PTEN upregulation mediated by HDAC2 and suppression of the PI3K/Akt pathways." (PMID 38445441, 2024). "The identification of safe and potent dual-targeting PKMYT1/HDAC2 inhibitors by molecular docking-based virtual screening is a particularly important strategy for the treatment of liver cancer." (PMID 39619613, 2024). "Herein, we report a discovery of novel and highly potent dual-targeting PKMYT1/HDAC2 inhibitors through virtual screening and subsequent biological evaluation for the treatment of liver cancer." (PMID 39619613, 2024). "Using the HPA database, we found that the protein expression level of EEF1E1 and HDAC2 were higher in liver cancer while lower in normal liver." (PMID 36189258, 2022). "Among the screened EMT-related genes, some have already been extensively studied in liver cancer, especially HDAC2." (PMID 35517787, 2022). "The risk score calculated by the expression value of HDAC1, HDAC2, HDAC4, HDAC11, HAT1, and SIRT6 was an independent risk factor for liver cancer." (PMID 36124029, 2022). "To generalize this finding to liver cancer cells, we employed three more different liver cancer cell lines and investigated the tumor suppressing effects of HDAC2-targeting upon tumor cell growth." (PMID 22132221, 2011). "Furthermore, butyrate promotes liver cancer metastasis by increasing the expression of H19 in tumor cells through the inhibition of HDAC2, leading to increased H3K27 acetylation at the H19 promoter and inducing M2 macrophage polarization." (PMID 40299650, 2025). "However, to our knowledge, there have been no reports to date of dual-targeting inhibitors for PKMYT1, a member of the WEE kinase family, and HDAC2 for the treatment of liver cancer." (PMID 39619613, 2024). "Therefore, we defined HDAC2 as a new potential target for the treatment of liver cancer that acquired sorafenib resistance." (PMID 37248230, 2023). "Interestingly, we also found that HDAC2 levels in secondary liver cancer tissues are higher than those in normal liver tissues, which further supports that HDAC2 plays an important role in the progression of liver cancer." (PMID 36189258, 2022). "Although we showed that ectopic miR-31 elicited inhibition of cellular growth of liver cancer cells through targeting HDAC2, it is necessary to prove that ectopic overexpression of 3′ UTR-deleted HDAC2 plasmid (pME18s-HDAC2-FLAG) can rescue the effects on cell cycle molecules in the same cells." (PMID 25797269, 2015). "We have also reported that overexpression of HDAC2 was found in stomach and liver cancer." (PMID 22132221, 2011). "In conclusion, we suggest that the aberrant regulation of HDAC2 may play a pivotal role in the development of HCC through its regulation of cell cycle components at the transcription level providing HDAC2 as a relevant target in liver cancer therapy." (PMID 22132221, 2011). "Using oleanolic acid-related liver cancer sequencing data, we found that oleanolic acid decreased the expression of HDAC1 and HDAC2 and increased the expression of HMOX1 and HMOX2." (PMID 38127054, 2023). "Using sequencing data related to liver cancer and cirrhosis, we found that HDAC1 and HDAC2 expression was elevated in liver cancer and cirrhosis, and HMOX1 and HMOX2 expression was decreased." (PMID 38127054, 2023). "Taken together, we present evidences that miR-31 functions as a tumor suppressive miRNA by directly regulating HDAC2 and CDK2 expression in liver cancer progression." (PMID 25797269, 2015). "Our results showed that ectopic expression of miR-31 resulted in suppression of HDAC2 and CDK2 protein expression in liver cancer cells." (PMID 25797269, 2015).
liver cancer (continued). "Our results showed inhibition of DNA methylation by either 5-aza-dC treatment or knockdown of DNMT1 caused the induction of miR-31 expression, and consequently suppressed HDAC2 and CDK2 expression in liver cancer cells." (PMID 25797269, 2015). "Among liver cancer cell lines, we selected HepG2, SNU-182 and SNU-449 cell lines as they exhibited relatively high expression for HDAC2 in Western blot analyses." (PMID 22132221, 2011). "Inhibition of HDAC2 expression promotes histone acetylation in the MIR22HG promoter region, thereby up-regulating the expression of MIR22HG and promoting the production of miR-22-5p, and ultimately increasing the sensitivity of liver cancer radiotherapy." (PMID 33718133, 2021). "The inhibition of HDAC2 expression promotes histone acetylation in the MIR22HG promoter region, thereby up-regulating MIR22HG expression and promoting the production of miR-22-5p, ultimately increasing the sensitivity of liver cancer radiotherapy." (PMID 33718133, 2021). "Additionally, the score for patients with HDAC8 expression in liver cancer is notably lower (9%) compared to other members—HDAC1: 90%, HDAC2: 75% and HDAC3: 50%." (PMID 30691229, 2019). "Notably we also found that treatment of DZNep elicited remarkable suppression of EZH2, HDAC2 and CDK2 proteins with concomitant increase of miR-31 expression in liver cancer cells." (PMID 25797269, 2015). "These suggest that activation of Wnt signaling and/or c-Myc may not contribute to aberrant regulation of HDAC2 in liver cancers." (PMID 22132221, 2011).